EFTUD2 (elongation factor Tu GTP binding domain containing 2)
Diseases named in the same sentence as EFTUD2 in open-access papers (continued):
Sharing a sentence is not in itself a finding about the gene and the disease.
tumor (continued). "As an important splicing factor protein, EFTUD2 may indirectly promote the progression of LUAD by affecting the RNA splicing of other tumor-related genes." (PMID 40236649, 2025). "This is particularly interesting given the observed variability in EFTUD2 expression within tumor samples, suggesting that while EFTUD2 is generally upregulated in tumors, its reduced expression might indicate a more aggressive disease." (PMID 40650074, 2025). "Studies found that the expression level of EFTUD2 was markedly increased in tumor tissues." (PMID 40116087, 2025). "Conversely, overactivation of EFTUD2 may promote LUAD tumor proliferation and elevate lactate metabolism levels in both the tumors and the host." (PMID 40236649, 2025). "Also, a reduced tumor growth in case of EFTUD2 knockdown was detected, suggesting it as an independent prognostic factor for patients with hepatic cellular cancer." (PMID 36068443, 2023). "Literature evidence suggests that elongation factor Tu GTP binding domain containing 2 (EFTUD2) and prominin (PROM1) gene expression have significant diagnostic potential in early tumor detection, potentially reflecting the trends in progression, and may become a novel therapeutic target." (PMID 40650074, 2025). "Furthermore, EFTUD2 may promote the development of a tumor immune microenvironment (TIME) that facilitates immune escape in LUAD tumor cells by regulating the expression of glycolytic enzymes." (PMID 40236649, 2025). "EFTUD2 was upregulated in LUAD tissues and cells, correlating with N classification, visceral pleural invasion, intravascular tumor embolism, and cytokeratin-19 fragment antigen 21-1." (PMID 40236649, 2025). "The helicase RIG-I, a part of the innate immune system, and EFTUD2, a splicing factor which can upregulate RIG-I expression, are shown to influence tumor growth and disease progression in several malignancies." (PMID 36068443, 2023). "Notably, both HNRNPC and IGF2BP2 promote tumor aerobic glycolysis, and our GSEA revealed that EFTUD2 upregulation was significantly and positively correlated with glycolysis." (PMID 40236649, 2025). "Intriguingly, while these associations were significant, we did not observe a noteworthy link between EFTUD2 and lymphatic invasion, distant metastasis (pathologic M stage), and tumor location (anatomic neoplasm subdivision)." (PMID 38163859, 2024).
infection (8 papers, 2016 to 2025). The state of being infected such as from the introduction of a foreign agent such as serum, vaccine, antigenic substance or organism. "Knockdown of two proteins (EFTUD2 and SNRNP200) belonging to the U5 snRNP family resulted in a reduction of p-MLKL after infection of L929 cells with reovirus T3DS (reovirus variant derived from the Lemay lab)." (PMID 36768641, 2023). "Since EFTUD2-depleted cells survive longer after infection, this increased survival is also accompanied by prolonged viral replication beyond the normal replication cycle." (PMID 36560714, 2022). "Conversely, EFTUD2 knockdown reduced chMDA5 expression under infection conditions." (PMID 40580566, 2025). "In addition, we stably knocked down EFTUD2 expression in Hep3B and Huh7 cells by infection with lentivirus vectors." (PMID 33024090, 2020). "We previously demonstrated that MRV reduces the protein levels of EFTUD2, PRPF8, and SNRNP200 through the action of the μ2 protein during infection." (PMID 36560714, 2022). "The structural protein μ2 appears to be the main determinant of these AS modifications by decreasing the levels of U5 core components EFTUD2, PRPF8, and SNRNP200 during infection." (PMID 36614170, 2022). "Together, these data show that U5 snRNP proteins EFTUD2 and SNRNP200 are involved in cell survival and/or cell death after infection with MRV." (PMID 36560714, 2022). "EFTUD2 and SNRNP200 are thus required for induction of necroptosis during MRV infection while EFTUD2’s importance for necroptosis appears to be generalized to other necroptotic stimuli, such as zVAD-fmk/TNFα." (PMID 36560714, 2022). "μ2 impacts cellular AS by interacting with U5 snRNP proteins EFTUD2, PRPF8, and SNRNP200, and reducing their levels during infection." (PMID 36560714, 2022). "We first questioned if KD of EFTUD2 and SNRNP200 impacted apoptosis to enhance cell survival after MRV infection by using a high-throughput microscopy-based assay." (PMID 36560714, 2022). "Surprisingly, T3DS infection led to a striking reduction in PRPF8 (80%) protein levels, and a more modest reduction in EFTUD2 (35%) and SNRNP200 (25%)." (PMID 35489070, 2022). "In conclusion, EFTUD2 plays a crucial role in various non-neoplastic diseases, affecting craniofacial development, the nervous system, circulatory function, digestion, reproduction, the musculoskeletal system and immune responses to infections." (PMID 40116087, 2025). "Moreover, EFTUD2 and PRPF8 control the induction of the IFN response pathway, establishing the U5 snRNP as a potent target for viruses to abrogate the cellular response mounted against infection." (PMID 36560714, 2022). "In contrast, no significant changes were observed for CD2BP2, DDX23, EFTUD2, SNRNP40 (U5 snRNP components) or SF3A2 (U2 snRNP component) levels up to 48 hours of infection as compared with those in uninfected cells." (PMID 27575636, 2016). "We also validated that the depletion of EFTUD2, PRPF8, and SNRNP200 was not decreasing cell viability, and that cell survived and even expanded throughout the course of the experiment in the absence of infection." (PMID 36560714, 2022).
genetic disorders (3 papers, 2021 to 2025). "PRPF6, PRPF8, and EFTUD2 have all been associated with genetic disorders (RP and MFDGA, respectively), and in all cases it is proposed that the causative variants result in the mis-splicing of particular pre-mRNAs relevant for the disorder phenotype." (PMID 33584830, 2021).
neurodevelopmental disorder (1 paper, 2025). A behavioral and cognitive disorder with onset during the developmental period that involves impaired or aberrant development of intellectual, motor, or social functions. "Further investigation is essential to elucidate the precise mechanisms by which EFTUD2 regulates these processes and contributes to neurodevelopmental disorders such as MFDM." (PMID 40448601, 2025). "By mechanistically linking EFTUD2 mutations to a unified pathway of splicing‐dependent apoptosis, this work repositions MFDM within the emerging class of spliceosomopathies and establishes a framework for targeted therapeutic development in neurodevelopmental disorders." (PMID 40448601, 2025).
psychiatric disorder (1 paper, 2025). A disorder characterized by behavioral and/or psychological abnormalities, often accompanied by physical symptoms. "Dysregulation of EFTUD2 plays a critical role in psychiatric disorders, such as attention deficit hyperactivity disorder and schizophrenia, by affecting target gene expression." (PMID 40116087, 2025).
skeletal dysplasia (1 paper, 2019). Any Mendelian diseases that affects growth and development of the skeleton. "Heterozygous loss of function variants of EFTUD2 was previously reported in MFDM; however, the mechanism underlying EFTUD2-associated skeletal dysplasia remains unclear." (PMID 31806011, 2019).
EFTUD2 also shares sentences with these, for which no sentence is quoted: hearing loss (2 papers); Treacher-Collins syndrome (2); achondroplasia (1); Areflexia (1); auditory neuropathy spectrum disorder (1); auriculocondylar syndrome (1); cardiac disease (1); cerebellar ataxia (1); Cerebro-costo-mandibular syndrome (1); choanal atresia (1); chromosomal deletion syndromes (1); Clear Cell Renal Cell Carcinoma (1); cleft lip (1); colitis (1); coloboma (1); colorectal tumors (1); Craniofacial dysostosis (1); craniofacial microsomia (1); developmental and epileptic encephalopathy (1); Fanconi Syndrome (1); Hirsutism (1); metopic craniosynostosis (1); Micrognathia (1); microtia (1); Miscarriage (1); movement disorder (1); Nager syndrome (1); optic atrophy (1); optic nerve hypoplasia (1); Pes cavus (1).
A further 7 diseases each share a sentence with EFTUD2 in 1 paper.